PSMC5 (proteasome 26S subunit, ATPase 5)
Diseases named in the same sentence as PSMC5 in open-access papers:
PSMC5 is named in the same sentence as 44 diseases in open-access papers, as found by Europe PMC text mining. Sharing a sentence is not in itself a finding about the gene and the disease. The quoted sentences say what the papers report.
colorectal cancer (6 papers, 2013 to 2026). A primary or metastatic malignant neoplasm that affects the colon or rectum. "In a recent study, PSMC5 methylation has been linked to being negatively associated with colorectal cancer exacerbation." (PMID 35938038, 2022). "In colorectal cancer, PSMC5 promoted cancer cell proliferation and metastasis by activating the epithelial-mesenchymal transition and modulating immune cell infiltration." (PMID 36498916, 2022). "We designed the present study to access the roles and mechanisms of PSMC5 in colorectal cancer (CRC)." (PMID 34336824, 2021). "Obviously, high expression of the four genes (DDX56, CTSL, ZC3H12D, and PSMC5) could promote the expression of PD-L1 as they have been proven to be promising biomarkers and immunotherapy targets in a variety of tumors, including colorectal cancer, NSCLC, and gastric cancer." (PMID 35647031, 2022).
Cognitive Deficits (3 papers, 2020 to 2023). "Regulating the expression of PSMC5 could have important therapeutic implications for treating neurodegenerative diseases involving neuroinflammation-associated cognitive deficits and motor impairments induced by microglial activation." (PMID 38001534, 2023). "PSMC5 could be an important therapeutic target for treatment of neurodegenerative diseases involving neuroinflammation-associated cognitive deficits and motor impairments induced by microglial activation." (PMID 38001534, 2023).
developmental delay (3 papers, 2023 to 2025). "In this study, whole-exome sequencing (WES) identified a de novo variant, c.959C>G (p.Pro320Arg), in the PSMC5 gene in a patient presenting with global developmental delay and mild intellectual disability." (PMID 40650163, 2025). "In the present study, we identified the c.959C>G (p.Pro320Arg) variant in the PSMC5 gene in a patient diagnosed with global developmental delay and mild intellectual disability." (PMID 40650163, 2025). "The first de novo PSMC5 missense variant (c.959C>G p.P320R) was detected in two patients (Cases 1 and 2), both showing moderate to severe developmental delay, speech delay, motor delay, and intellectual disability." (PMID 38776958, 2024).
Parkinson disease (3 papers, 2022 to 2025). A progressive degenerative disorder of the central nervous system characterized by loss of dopamine producing neurons in the substantia nigra and the presence of Lewy bodies in the substantia nigra and locus coeruleus. "In comprehensive bioinformatics analysis studies, Psmc5 has been identified as an essential protein involved in respiratory diseases, Parkinson's disease, and many other neurodegenerative diseases." (PMID 35237384, 2022).
breast carcinoma (2 papers, 2021 to 2022). "The data demonstrated that PSMC1-6 presented moderate protein expressions, and PSMC2, PSMC3, and PSMC5 were highly expressed in certain clinical tissues from breast cancer specimens." (PMID 34329194, 2021). "Both mRNA and protein levels of PSMC2, PSMC3, PSMC4, PSMC5, and PSMC6 were significant in cancer tissues, and PSMC1, PSMC3, PSMC4, PSMC5, and PSMC6 overexpression was associated with poor prognoses of breast cancer patients." (PMID 34329194, 2021). "According to our results from an Oncomine analysis of mRNA expressions of PSMC2, PSMC3, PSMC4, PSMC5, and PSMC6, these members are highly upregulated in breast cancer tissues; therefore, we chose breast cancer to perform further bioinformatics analyses." (PMID 34329194, 2021). "Meanwhile, we discovered that high levels of PSMC1, PSMC3, PSMC4, PSMC5, and PSMC6 transcripts were positively correlated with poor survival, which likely shows their importance in breast cancer development." (PMID 34329194, 2021). "The present findings showed significantly higher expression profiles of PSMC2, PSMC3, PSMC4, PSMC5, and PSMC6 in breast cancer compared to normal breast tissues." (PMID 34329194, 2021). "Indeed, PSMC2, PSMC3, PSMC4, PSMC5, and PSMC6 were recently reported as highly expressed in breast cancer, which correlated with worse outcomes." (PMID 36498916, 2022). "The Kaplan–Meier plotter database also showed that PSMC1, PSMC3, PSMC4, PSMC5, and PSMC6 had high expression levels in breast cancer tissues may have oncogenic roles in breast cancer progression." (PMID 34329194, 2021).
Intellectual disability (2 papers, 2024 to 2025). "In this study, we initially ascertained two unrelated individuals both carrying the identical de novo P320R mutation in PSMC5 presenting with neurodevelopmental delay and intellectual disability." (PMID 38776958, 2024).
neuroblastoma (2 papers, 2024 to 2025). Neuroblastoma (NB) is the most common solid, extracranial childhood tumor. "PSMC5 was knocked down in human cervical cancer HeLa cells and human neuroblastoma SH-SY5Y cells." (PMID 38776958, 2024).
viral infection (2 papers, 2018 to 2025). "We studied the effects of Psmc5 loss on primary rat hippocampal neurons by gene KD, using Psmc5-specific shRNA or scrambled shRNA for controls (scrambled Ctrl) along with co-expressed GFP delivered via lenti-virus infection of cells at day in vitro 1 (DIV1)." (PMID 41298377, 2025). "Eight proteins (GPT2, HSPA9, MAPK1, PDIA3, PDIA6, PSMC5, TALDO1, and ATP5B) were predicted/known to be involved in viral infection." (PMID 29404200, 2018). "The change in abundance of eight of the targeted proteins (GPT2, HSPA9, MAPK1, PDIA3, PDIA6, PSMC5, TALDO1, and ATP5B) was predicted to collectively inhibit viral infection (pathway analysis)." (PMID 29404200, 2018). "Analysis using IPA software suggested that eight of the targeted proteins (ATP5B, GPT2, HSPA9, MAPK1, PDIA3, PDIA6, PSMC5, and TALDO1) were involved in virus infection and their lower protein abundance may inhibit viral infection." (PMID 29404200, 2018).
colon cancer (1 paper, 2022). "First, high levels of CD46-9652-ES and PSMC5-43011-ES were proven in colon cancer." (PMID 35692800, 2022). "Additionally, the in vitro experiment validated that CD46-9652-ES and PSMC5-43011-ES are positively correlated with the infiltration of immune cells and promote the growth of colon cancer cells." (PMID 35692800, 2022). "Additionally, PSMC5 was observed to be associated with the infiltration of immune cells, including M2 macrophages, in the tumour microenvironment, and our study further indicated that the specific AS of PSMC5 in colon cancer cells could induce M2 polarization of macrophages." (PMID 35692800, 2022). "We next investigated the CD46-9652-ES and PSMC5-43011-ES levels in 20 colon cancer samples characterized by CD4+/CD4- T cell infiltration and 20 colon cancer samples characterized by high/low M2 macrophage infiltration." (PMID 35692800, 2022).
glioma (1 paper, 2021). A benign or malignant brain and spinal cord tumor that arises from glial cells (astrocytes, oligodendrocytes, ependymal cells). "Conversely, PSMC5 was significantly associated with better overall survival of the glioma patients (P < 0.05)." (PMID 34804978, 2021). "All the results confirmed that PSMD3 and PSMC5 can be identified as potential biomarkers in glioma patients." (PMID 34804978, 2021). "Furthermore, the high risk score hinted an immunosuppressive microenvironment and a lower sensitivity of immune checkpoint blockade therapy and also identified PSMC5 and PSMD3 as novel biomarkers in glioma." (PMID 34804978, 2021). "In addition, a high risk score hinted an immunosuppressive microenvironment and lower sensitivity of ICB therapy, and PSMC5 and PSMD3 were identified as novel biomarkers in glioma." (PMID 34804978, 2021). "Inversely, the expression level of PSMC5 was negative with the grade of glioma." (PMID 34804978, 2021). "Besides this, we also have identified PSMC5 and PSMD3 as new biomarkers in glioma." (PMID 34804978, 2021).
language delay (1 paper, 2024). "Additionally, 2 further cases with very similar clinical profile of neurodevelopmental delay and speech and language delay with the PSMC5 P320R mutation are visible in DECIPHER." (PMID 38776958, 2024).
leukemia (1 paper, 2019). A malignant (clonal) hematologic disorder, involving hematopoietic stem cells and characterized by the presence of primitive or atypical myeloid or lymphoid cells in the bone marrow and the blood. "Many research demonstrated the role of CBLB in leukemia, while PSMC5 and PSMD11 were only reported to be involved in cancer development in very recent studies." (PMID 31874600, 2019).
lung carcinoma (1 paper, 2021). "Moreover, expression of PSMC5 was shown to be related with response to ICB therapy in other cancers including lung cancer, melanoma, and urothelial cancer, which suggested that PSMC5 might be a potential marker or a target for ICB therapy in CRC patients." (PMID 34336824, 2021).
melanoma (1 paper, 2021). A malignant, usually aggressive tumor composed of atypical, neoplastic melanocytes. "Similarly, PSMC5 was found to be either positively or negatively associated with treatment response of several cancers including melanoma, urothelial cancer, and non-small cell lung cancer." (PMID 34336824, 2021). "Moreover, PSMC5 was associated with response of immune therapy for several types of cancer such as melanoma, non-small cell lung cancer, and urothelial cancer." (PMID 34336824, 2021).
ovarian carcinoma (1 paper, 2022). A malignant neoplasm originating from the surface ovarian epithelium. "First, we evaluated the expression levels of the six PSMC family members in 24 types of cancer in TCGA database and found that PSMC5 was the most predominant in all types of cancer except ovarian cancer, whereas PSMC2 and PSMC6 had a relatively lower expression level in pan-cancer." (PMID 36699466, 2022).
rectal adenocarcinoma (1 paper, 2021). "To further investigate the molecular mechanisms of PSMC5 in CRC progression, we dichotomized RNA expression data from TCGA COAD and rectal adenocarcinoma into PSMC5-high and PSMC5-low groups." (PMID 34336824, 2021).
thyroid (1 paper, 2025). "We hypothesize that the de novo variant identified in the PSMC5 gene may contribute to the development or worsening of thyroid abnormalities in the patient." (PMID 40650163, 2025).
cancer (11 papers, 2010 to 2024). A tumor composed of atypical neoplastic, often pleomorphic cells that invade other tissues. "In this study, we firstly reported that the expression of PSMC5 was higher in cancer tissues compared with normal tissues, and high expression of PSMC5 was associated with poor prognosis of CRC patients." (PMID 34336824, 2021). "Genes shared by cluster A and D represent a link between chromatin organization and cancer hallmark processes, involving FOXA1, ESRI, PHF14 and the ATPase proteasome subunits, PSMC5 and PSMC4." (PMID 38625038, 2024). "Consistently, gain of PSMC5 was also observed in multiple human cancer cell lines including several CRC cell lines." (PMID 34336824, 2021). "The results showed that PSMC5 was significantly higher in cancer than normal tissues." (PMID 34336824, 2021). "Consistently, higher PSMC5 expression was found in 62.2% (23/37) of cancer tissues." (PMID 34336824, 2021). "PSMC5 acts as a novel regulator and is involved in the extracellular signal-regulated kinase 1/2 signaling pathway, and it was observed to have a relatively higher cytoplasmic expression pattern in most cancer types." (PMID 34329194, 2021). "Compared with the diploid, other types (deep deletion and shallow deletion gain amplification) of CNV were significantly correlated with gene expressions of DDX56, ZC3H12D, and PSMC5 (p < 0.05), except for CTSL (p > 0.05), indicating that CNV might regulate the expression of these genes in cancer." (PMID 35647031, 2022). "The observed anti-cancer effects of PIAS2b-dsRNAi in both thyroid and non-thyroid anaplastic cells, including downregulation of PLK1, gTub, CDK1, and the presence of high-molecular weight PP2CA and PSMC5 bands, might be linked to this dysregulated proteasome activity." (PMID 38744818, 2024). "Interestingly, we discovered that PSMC genes were overexpressed in a subtype-specific manner: specifically, PSMC1, PSMC2, PSMC3, PSMC4 were highly expressed in the triple-negative subtype, PSMC5 in HER-2, and PSMC6 in luminal cancer." (PMID 34329194, 2021).
tumor (11 papers, 2014 to 2026). "Firstly, high PSMC5 expression was associated with lower tumor purity and higher immune score, indicating that PSMC5 might regulate immune cell accumulation in the microenvironment of CRC." (PMID 34336824, 2021). "Besides, PSMC5 was associated with more advanced tumor stage." (PMID 34336824, 2021). "In vivo, SMURF1 silencing restored METTL14 expression and attenuated PSMC5-driven tumor growth and lung metastasis." (PMID 42212325, 2026). "As expected, a higher PSMC5 level was significantly linked to expression of CD274 (PD-L1), CTLA-4, and IDO1 in CRC tumor cells, indicating a potential role of inhibiting PSMC5 in immune checkpoint blockade (ICB) therapy." (PMID 34336824, 2021). "Moreover, we enrolled 37 cases CRC patients in our institute and identified PSMC5 expression with immunohistochemistry staining of tumor and paired normal tissues." (PMID 34336824, 2021). "Animal studies revealed that knockdown of PSMC5 inhibited tumor growth in nude mice." (PMID 34336824, 2021). "As expected, PSMC5 was linked to multiple intracellular events such as chemokine binding, growth factor activity, and immunoglobulin binding, which might account for its potential interaction with EMT and tumor immune response." (PMID 34336824, 2021). "DNA sequencing of the tumor tissue identified a fusion involving exons 1–16 of EWSR1 and exon 12 of PSMC5." (PMID 39877461, 2025). "The molecular mechanisms by which PSMC5 regulates CRC cells include the activation of epithelial–mesenchymal transition (EMT) and alteration of immune infiltrates in the tumor microenvironment (TME)." (PMID 34336824, 2021). "The expression of three antigens (MYPT1, PSMC5 and TRFR) was measured in tumor and normal duct epithelium, and significant differences were found in the expression of these three antigens in tumor compared with normal tissue." (PMID 27532021, 2016). "Using this assay, several new tumor antigens (MYPT1, PSMC5 and TRFR) were identified that were found to have significantly different expression in tumors compared with normal tissue." (PMID 27532021, 2016). "Nevertheless, the roles and functions of PSMC5 in tumor, especially in CRC, have not been fully investigated." (PMID 34336824, 2021). "Knockdown of PSMC5 led to suppression of EMT and tumor metastasis, which may be a promising treatment strategy for CRC." (PMID 34336824, 2021). "Finally, we validated their expression using qPCR in an additional set of tumor:matched normal samples that resulted in five genes (RPL30, RPL27, PSMC5, MTCH1, and OAZ1), out of which RPL30 and RPL27 were most stable and were abundantly expressed across the tissues." (PMID 30128175, 2018).
neurodegenerative disease (5 papers, 2021 to 2025). A disorder of the central nervous system characterized by gradual and progressive loss of neural tissue and neurologic function. "A high abundance of WNT, SEMG1, PSMB3, PSMC5, and other proteins in the advanced age group may be associated with risk for neurodegenerative diseases, malignancies, and impact sperm DNA integrity, spermatozoa survival and function, and fertilization." (PMID 40649876, 2025).
infection (4 papers, 2013 to 2023). The state of being infected such as from the introduction of a foreign agent such as serum, vaccine, antigenic substance or organism. "In order to decrease intracellular PSMC5 protein levels, we performed intracerebroventricular (i.c.v.)infection with a lentivirus carrying shRNA PSMC5 in the mice, which decreased PSMC5 protein levels in the absence or presence of LPS stimulation in the brain tissues." (PMID 38001534, 2023).
neurodevelopmental disorder (3 papers, 2024 to 2025). A behavioral and cognitive disorder with onset during the developmental period that involves impaired or aberrant development of intellectual, motor, or social functions. "This study aims to strengthen the association between PSMC5 and neurodevelopmental disorders, corroborating evidence reported in previous research." (PMID 40650163, 2025). "Our study supports that proteasome dysfunction is the pathogenic cause of neurodevelopmental disorders in individuals carrying PSMC5 variants." (PMID 38776958, 2024). "We believe that the findings of this study may support the inclusion of PSMC5 among the genes associated with neurodevelopmental disorders with an associated MIM phenotype number." (PMID 40650163, 2025). "Additionally, two small deletions are listed, both classified as VUSs; notably, the p.Lys393del variant (VCV003600378.1) has been linked to a “PSMC5-related neurodevelopmental disorder”." (PMID 40650163, 2025). "Thus, it seems possible that defective or deficient PSMC5 contributes to the pathogenesis of neurodevelopmental disorders." (PMID 38776958, 2024). "Here we identified mutations in PSMC5, an AAA ATPase subunit of the proteasome 19S regulatory particle, in individuals with neurodevelopmental disorders, which were initially considered as variants of unknown significance." (PMID 38776958, 2024).
head and neck tumor (1 paper, 2018). "Our data suggest that RPL30 or RPL27 in combination with either PSMC5 or MTCH1 or OAZ1 can be used as a minimal set of control genes in head and neck tumor gene expression studies." (PMID 30128175, 2018).
PSMC5 also shares sentences with these, for which no sentence is quoted: bacterial infection (2 papers); amyotrophic lateral sclerosis (1); autism (1); autism spectrum disorder (1); bbs (1); cervical cancer (1); developmental verbal dyspraxia (1); diabetes (1); gastric cancer (1); Huntington disease (1); immune deficiency (1); Lewy body dementia (1); lipodystrophy (1); liver cancer (1); Motor delay (1); Neurodevelopmental delay (1); non-small cell lung carcinoma (1); osteosarcoma (1); pancreatic cancer (1); prion disease (1); respiratory diseases (1).